LEP (leptin)
Diseases named in the same sentence as LEP in open-access papers (continued):
Sharing a sentence is not in itself a finding about the gene and the disease.
preeclampsia (continued). "Leptin levels were significantly higher (p < 0.0002) in women with preeclampsia compared to controls." (PMID 36034841, 2022). "Leptin is involved in trophoblast invasiveness, and its dysregulation is connected with a series of diseases, including preeclampsia." (PMID 36457544, 2022). "Our meta-analysis supports these results since leptin was also found to be increased in patients with preeclampsia." (PMID 36034841, 2022). "This study was aimed at determining the levels of serum adiponectin, leptin, resistin, visfatin and lipids during the first trimester in pregnant women and to evaluate the relationship between these biochemical markers and preeclampsia (PE)." (PMID 33014422, 2020). "Our observations are similar to the results of previous studies conducted in preeclamptic patients which have suggested a positive correlation between elevated serum leptin levels and preeclampsia." (PMID 31737362, 2019). "In contrast to adiponectin and leptin, studies about the regulation of chemerin, visfatin, resistin and apelin in gestational diabetes, preeclampsia and intrauterine growth restriction are limited." (PMID 31505789, 2019). "It was reported that chronic plasmatic leptin elevations in pregnant rats, increased blood pressure and placental factors that have a role in preeclampsia." (PMID 30618843, 2018). "The RUPPrat mimics numerous physiological features of preeclampsia in women, includinghypertension, proteinuria, impaired renal function, and increased vascularreactivity, leptin, and blood lactate." (PMID 29898033, 2018). "In support of this proposal, it has been reported that pregnant obese women that develop preeclampsia have increased leptin levels in relation to healthy pregnant women." (PMID 30618843, 2018). "Elevations in circulating leptin are associated to increased circulating levels of TNF-α in obese pregnant rats, and we have shown that women with preeclampsia have increased levels of TNF-α, IL-6 and C-reactive protein (CRP)." (PMID 30618843, 2018). "Higher adiponectin serum and leptin levels in preeclampsia mothers have also been described by other authors." (PMID 29212463, 2017). "Women with preeclampsia display significantly higher serum leptin levels than healthy pregnant women." (PMID 24991435, 2014). "An intriguing finding of our study is that increased serum levels of leptin were related to those of interferon-γ-inducible protein (IP)-10 both in normal pregnancy and preeclampsia, as shown by the significant correlations between these variables." (PMID 21906313, 2011). "As placenta produces leptin, its hypoxia, occurred in preeclampsia, is likely to enhance leptin production." (PMID 25587260, 2011). "Further longitudinal studies are required to clarify the predictive value of circulating leptin in preeclampsia." (PMID 21906313, 2011). "Since lower serum leptin concentrations were detected in neonates of pre-eclamptic group, more extensive studies should be designed to determine the role of leptin in preeclampsia." (PMID 25587260, 2011). "Therefore, it may be assumed that oxidative stress would be associated with leptin in preeclampsia." (PMID 25587257, 2011). "Plasma leptin levels are significantly elevated in pregnant women with PE and the increase in plasma leptin levels is correlated with the severity of preeclampsia." (PMID 21048973, 2010). "In other words, leptin is a biomarker of women with preeclampsia during pregnancy." (PMID 40990740, 2025). "In the following sections, we will discuss the role of insulin and leptin in preeclampsia as these factors are altered in the obese mouse model of preeclampsia—i.e., feeding ASB4-null mice with a high-fat diet (HFD), as described in the last section of this review." (PMID 39201703, 2024). "When we consider hyperleptinemia observed in preeclampsia, a disorder of insufficient trophoblast invasion, excess leptin may be hindering placental invasion as part of the pathologic process." (PMID 38846494, 2024).
preeclampsia (continued). "Additionally, maternal serum leptin concentrations are higher in preeclampsia compared to normotensive pregnancies." (PMID 38605139, 2024). "Leptin’s differential effect on trophoblast invasion may explain the role of hyperleptinemia in preeclampsia pathogenesis." (PMID 38846494, 2024). "Haugen and coworkers analyzed the leptin status of pre-eclamptic mothers and found that the concentration of leptin in the plasma of pregnant women with preeclampsia was significantly higher than in the plasma of women in physiological pregnancy (34.4 ± 3.2 ng/mL and 22.3 ± 1.1 ng/mL, respectively)." (PMID 37764842, 2023). "For example, analyzing and monitoring levels of leptin, adiponectin, FT4, insulin and CRP could assist in early identification of women at risk for preeclampsia or development of GDM." (PMID 36520252, 2023). "However, it is crucial to recognize that the exact role of leptin in preeclampsia's development remains incompletely understood." (PMID 38099221, 2023). "In a cross-sectional study, results were obtained suggesting that the leptin/adiponectin ratio increases in preeclampsia and that the imbalance between adipocytokines may play a role in the pathogenesis of preeclampsia." (PMID 35206438, 2022). "Thus, the role of LEP in the occurrence and development of preeclampsia was explored by targeting LEP." (PMID 36685185, 2022). "Thus, after controlling for Bishop score and preeclampsia, leptin was still predictive of successful IOL with an odds ratio of 0.47 (P = 0.046)." (PMID 35031012, 2022). "Exosomal miR-18b-3p derived from hucMSCs inhibits preeclampsia by targeting leptin (LEP)." (PMID 36548867, 2022). "We concluded that some inflammatory markers in our meta-analysis such as leptin, total cholesterol, triglycerides, TNFα and C-reactive protein were increased in pregnant women with preeclampsia compared to pregnant control women, so inflammatory markers are important markers of preeclampsia." (PMID 36034841, 2022). "The dysregulation of placental leptin was suggested in the pathogenesis of numerous pregnancy-related pathologies, including gestational diabetes, recurrent miscarriage, intrauterine growth retardation, and preeclampsia." (PMID 33801130, 2021). "Likewise, leptin protein and mRNA levels are also increased in the placenta of women with preeclampsia." (PMID 34440184, 2021). "CRP levels are positively correlated with leptin levels in women with preeclampsia." (PMID 31914480, 2020). "A very recent systematic review reported a significant association of high serum leptin levels with preeclampsia, regardless of the onset of preeclampsia or its severity." (PMID 32807109, 2020). "In addition, a gene microarray study demonstrate that a high expression of the leptin gene is present in pregnant women with preeclampsia." (PMID 32807109, 2020). "Third, high leptin levels may promote preeclampsia through altering insulin levels, signalling transduction, reaction with other proteins and metabolism." (PMID 32807109, 2020). "The higher leptin levels in PE could result from placental stress to increase nutrient delivery to the fetus or it could be related to an augmented leptin expression by the hypoxic placenta in preeclampsia." (PMID 31737362, 2019). "There is a growing body of evidence that leptin may play a direct role in the pathogenesis of preeclampsia." (PMID 31737362, 2019). "The higher levels of leptin in pregnant women with gestational hypertension may be suggestive of the role of leptin in GH development." (PMID 31737362, 2019). "This study identifies, higher levels of leptin expressions in umbilical cord from preeclampsia placenta, suggesting that provocation of interleukin-8 secretion by leptin in endothelial cells may contribute to preeclampsia-related inflammation." (PMID 29379664, 2017). "Amalet al reported that maternal serum leptin is significantly elevated in preeclampsia." (PMID 26000008, 2015).
preeclampsia (continued). "In accordance with the altered trophoblast pathophysiology in early-onset preeclampsia, many of the most differentially regulated genes in women with preeclampsia (LEP, CGB, LHB, INHA, SIGLEC6, PAPPA2, and FLT1) have predominant or unique expression in the syncytiotrophoblasts." (PMID 24991435, 2014). "Moreover, leptin levels are increased under stressful condition for placenta cells such as preeclampsia or gestational diabetes." (PMID 24922063, 2014). "In accordance with this finding, leptin is increased in circulation of preeclampsia patients." (PMID 22929622, 2012). "In addition, the expression OPG is the same as other hormones, such as Leptin, IGF-1 and adiponectin/receptor, which are associated with the pathogenesis of preeclampsia." (PMID 22952959, 2012). "Finally, the most strikingly gene altered in preeclampsia is LEP, which is up-regulated reported by multiple microarray studies, supporting the previous results." (PMID 22929622, 2012). "Simultaneous measurement of leptin with C-reactive protein, several cytokines, chemokines, adhesion molecules and angiogenic factors in this study enabled us to investigate their relationship, which can help to understand the role of circulating leptin in normal pregnancy and preeclampsia." (PMID 21906313, 2011). "Nevertheless, increased levels of anti-angiogenic factors such as sFlt-1 in the maternal circulation in normal pregnancy and preeclampsia might blunt this beneficial direct effect of leptin on angiogenesis." (PMID 21906313, 2011). "Interestingly, placental expression of leptin has been observed to be raised in preeclampsia by several research groups, including ours." (PMID 21906313, 2011). "Simultaneous measurement of leptin with several inflammatory molecules and angiogenic factors in this study enabled us to investigate their relationship, which can help to understand the role of circulating leptin in normal pregnancy and preeclampsia." (PMID 21906313, 2011). "Most of the available data suggest that the mean levels of leptin appear to be elevated in growth-restricted fetuses compared to appropriately grown controls, a difference that becomes further aggregated when growth restriction is accompanied by the development of preeclampsia." (PMID 38541892, 2024). "Moreover, leptin plays a key role in the immune mechanisms regulating implantation, trophoblastic invasion and placental angiogenesis, and persistently high levels of leptin in obese women are predictive of preeclampsia." (PMID 38417259, 2024). "Finally, to quantify the attenuation of differential expression of the preeclampsia biomarkers FLT1, LEP, and ENG, we applied mediation analysis to show cellular composition mediated a substantial proportion of the association between preeclampsia and FLT1, LEP, and ENG overexpression." (PMID 36914823, 2023). "Therefore, our study identified LEP as an important gene for preeclampsia." (PMID 37389124, 2023). "Since a significant elevation of leptin precedes the onset of clinical symptoms by several months, leptin, inhibiting inflammation and promoting angiogenesis, could possibly be served as a predictive marker for preeclampsia." (PMID 36172174, 2022). "The negative association with placental LEP methylation is in line with evidence of LEP hypomethylation in placenta of complicated pregnancies such as early-onset preeclampsia and impaired glucose metabolism, both known to adversely influence placental growth and vascularization." (PMID 27623604, 2017). "Nevertheless, preeclampsia may disrupt the association of maternal leptin levels with fetal growth, as shown by the lack of correlation with birth weight in our preeclamptic group." (PMID 21906313, 2011). "The biomarkers CGB5, LEP, LRRC1, PAPPA2, and SLC20A1 offer varying prospects for predicting preeclampsia." (PMID 39544937, 2024). "Preeclampsia placentas exhibited significantly elevated levels of NKRD37, CRH, LEP, and SIGLEC6 expression compared to the control group." (PMID 38894741, 2024).
preeclampsia (continued). "In comparison with the normal control group, the expression levels of the candidate genes ANKRD37, CRH, LEP, and SIGLEC6 in preeclampsia placenta were significantly increased, as visualized by the boxplot function." (PMID 38894741, 2024). "Then, immune microenvironment analysis turned out that M2 macrophages were reduced in preeclampsia women (p<0.0001) and were negatively correlated with the expression of PKM (r=-0.2, p<0.05), LEP (r=-0.4, p<0.0001), and HK2 (r=-0.3, p<0.001)." (PMID 38166707, 2024). "Employing weighted gene co-expression network analysis (WGCNA) and lasso regression, four potential target genes (ANKRD37, CRH, LEP, SIGLEC6) are identified for potential prediction of preeclampsia." (PMID 38894741, 2024). "In order to further understand the role of screened biomarkers in the diagnosis and prediction of preeclampsia, we based on the nomogram model of four key genes: ANKRD37, CRH, LEP, and SIGLEC6." (PMID 38894741, 2024). "From the heatmap, it can be observed that the expression of ANKRD37, CRH, LEP, and SIGLEC6 in preeclampsia placenta is significantly increased." (PMID 38894741, 2024). "In the cell type-naïve differential expression model, consistent with previous findings, placentas from pregnancies with preeclampsia overexpressed FLT1, LEP, and ENG59–62." (PMID 36914823, 2023). "A substantial proportion of the overexpression of the FLT1, LEP, and ENG in preeclampsia was mediated by placental cell composition." (PMID 36914823, 2023). "In the present study, we screened LEP, FLT1, RAB6C, and SASH1 as potential biomarkers for preeclampsia." (PMID 37389124, 2023). "The aim of this study was to assess the levels of adipokines such as leptin and adiponectin and the endothelium dysfunction markers: sICAM-1 and endogenous NOS inhibitor, ADMA, in pregnant women with gestational hypertension." (PMID 31737362, 2019). "So, the aim of this study was to evaluate the levels of adipokines such as adiponectin and leptin and the endothelium dysfunction markers: sICAM-1 and endogenous NOS inhibitor, ADMA, in pregnant women with gestational hypertension." (PMID 31737362, 2019). "Alternating O2 concentrations combined with ARNT2 or BCL6 overexpression led to the dysregulation of 11 genes (5 in the M2 and 3 in the M1 modules), including LEP, FLT1, and ENG, similar to preeclampsia." (PMID 30135684, 2018). "Two percent O2 induced the dysregulation of only five genes, including LEP and FLT1, from the set of genes investigated in the placenta in preterm preeclampsia, while alternating O2 concentrations induced the dysregulation of only three genes." (PMID 30135684, 2018). "Serum leptin was elevated in early onset preeclampsia (EOPE) and late onset preeclampsia (LOPE) compared to controls." (PMID 24591763, 2014). "qRT-PCR confirmed LEP and CRH increased, while SPP1 expression in preeclampsia samples." (PMID 39967661, 2025). "In summary, this research has identified PKM, LEP, and HK2 to be promising biomarkers for preeclampsia, which might regulate the pathogenesis of preeclampsia via targeting autophagy, metabolism and immune microenvironment." (PMID 38166707, 2024). "PKM, LEP, and HK2 could be promising biomarkers for preeclampsia, which might regulate the pathogenesis of preeclampsia via metabolism pathways and immune microenvironment." (PMID 38166707, 2024). "Plasma levels of leptin in pregnant women are 2–3 times higher than in non-pregnant women, and increased leptin concentrations in early pregnancy predict preeclampsia and gestational diabetes." (PMID 37964253, 2023). "In summary, LEP, FLT1, RAB6C, and SASH1 were identified as potential biomarkers of preeclampsia." (PMID 37389124, 2023). "Overall, while the mode of leptin action during preeclampsia is not yet fully determined, multiple studies agree that its levels are elevated in PE patients." (PMID 33321877, 2020).
preeclampsia (continued). "Interestingly and in accordance with the role of hypoxia in preeclampsia, HIF1A can regulate the expression of several top DEGs identified in the meta-analysis including: LEP, FLT1, INHA, BHLHE40, SPAG4, HK2, HILPDA and ERO1L." (PMID 27802351, 2016). "CREBBP interacts with several proteins well known to be associated with preeclampsia, such as NFE2L2, LEP and VEGF/FLT1, but also with proteins not-yet related to preeclampsia." (PMID 26171964, 2015). "FLT1, LEP, INHA and ENG genes were identified according to the literature, however, we also found other genes as FLNB, INHBA, NDRG1 and LYN highly significant but underexplored during normal pregnancy or preeclampsia." (PMID 24219996, 2013). "Thus, increased production of leptin, in combination with human chorionic gonadotropin (hCG) and other angiogenic factors secreted by the poorly perfused preeclamptic placenta, may be a compensatory mechanism against endothelial dysfunction observed in preeclampsia." (PMID 22929622, 2012). "LEP and ARHGEF4, involved in metabolic and hypoxia/angiogenesis pathways, are shown to be upregulated (in accordance with our result) in placentas from severe preeclampsia (sPE) patients across ancestries, suggesting its contribution to the pathophysiology of preeclampsia." (PMID 40357364, 2025). "However, some studies have not observed significant differences in leptin levels between pregnant women with preeclampsia and control." (PMID 37964253, 2023). "Therefore, it is not surprising that leptin has been measured in the amniotic fluid of women with preeclampsia." (PMID 37964253, 2023). "One review article suggests that intermittent hypoxia, a consequence of sleep-disordered breathing, may impact leptin levels in pregnant women, rather than preeclampsia's pathogenesis." (PMID 38099221, 2023). "The data we present here demonstrate a low-moderate correlation between leptin levels and BP parameters when ABPM is performed before the development of HDP, and this correlation is even stronger amongt women who subsequently develop gestational hypertension or preeclampsia." (PMID 36564806, 2022). "Furthermore, a comparison between PE and IUGR patients (without PE) showed that the levels of leptin were significantly lower in patients without preeclampsia, showing differences despite similar placental pathology." (PMID 33321877, 2020). "Previous research has shown that genetic variability in maternal LEP and LEPR gene might be involved in pathological processes in pregnancy, including preeclampsia and gestational diabetes mellitus, while the role of the LEP and LEPR gene in the IRSA has not been investigated." (PMID 28051281, 2016). "Circulating leptin levels are significantly higher in pregnant than in non-pregnant women, and there is a further increase in complicated pregnancies, such as gestational diabetes mellitus, preeclampsia and intrauterine growth restriction." (PMID 21906313, 2011). "In our study, the similar circulating leptin concentrations of preeclamptic patients regardless of the severity, the time of onset of the disease or the presence of fetal growth restriction might be explained by the multifactorial etiology of preeclampsia." (PMID 21906313, 2011). "However, increased sFlt-1 and decreased PlGF levels were not related to serum leptin concentrations in women with preeclampsia, suggesting that alterations in angiogenic cytokine profile and circulating levels of leptin are independent mechanisms in the pathogenesis of this multifactorial disorder." (PMID 21906313, 2011). "However, a previous study indicate that leptin has no role in the pathogenesis of preeclampsia and the increment in placental leptin expression may be attributed to the adaptive mechanism to hypoxia observed in preeclampsia." (PMID 32807109, 2020).